PPARG (peroxisome proliferator activated receptor gamma)
Diseases named in the same sentence as PPARG in open-access papers (continued):
Sharing a sentence is not in itself a finding about the gene and the disease.
Hepatic steatosis (continued). "With our previous findings that Vpr circulates in HIV patients (including those with undetectable plasma HIV-1 RNA), co-regulates the glucocorticoid receptor and PPARγ and transduces hepatocytes, these data indicate a potential role for Vpr in HIV-associated fatty liver disease." (PMID 29042644, 2017). "Since FSP27/CIDEC is involved in PPARγ-dependent hepatic steatosis, it is therefore necessary to determine whether the effects of PPARγ agonists on the formation of FL were mediated by activation of FSP27/CIDEC expression." (PMID 26770990, 2016). "The PPARγ agonist rosiglitazone, a potent insulin sensitizer, produces a marked worsening in oxidative stress and liver steatosis, indicating that the activation of PPARγ may induce steatosis." (PMID 26775807, 2016). "Moreover, PPARγ directly contributes to hepatic steatosis acting either down-stream or in parallel with SREBP-1." (PMID 27348013, 2016). "In hepatic steatosis, expression of several genes is dysregulated, including PPARγ and PPARα." (PMID 27611931, 2016). "Although these studies are restricted to non-alcoholic hepatic steatosis, we hypothesize that PPARγ and its downstream effector MGAT1 may play a role in alcohol-induced hepatic lipid accumulation if SIRT1 affects hepatic PPARγ during ethanol metabolism." (PMID 27404390, 2016). "However, the mechanism by which SIRT1 regulates hepatic PPARγ function, especially in alcoholic fatty liver, remains poorly understood." (PMID 27404390, 2016). "Increased PPARγ activity can lead to the development of fatty liver." (PMID 27348013, 2016). "In addition, Cidec has been identified as a PPARγ target and is a direct regulator of PPARγ-dependent hepatic steatosis." (PMID 27589064, 2016). "Similarly, other studies have shown that alcohol-mediated fatty liver and injury are prevented by PPARγ agonist presumably by activating c-Met and blocking alcohol-mediated induction of TNFα." (PMID 28074114, 2016). "PPARγ plays a crucial role in the development of hepatic steatosis." (PMID 26775807, 2016). "We also observed that PPARγ overexpression could induce hepatic steatosis, and that knockdown of MGAT1, a PPARγ target gene, could inhibit hepatic lipid accumulation." (PMID 27404390, 2016). "Interestingly, the novel PPARγ antagonist protopanaxatriol isolated from Panax ginseng improved liver steatosis in ob/ob mice." (PMID 27176632, 2016). "Combined with the gene expression data in liver, these data indicate that isorhamnetin may alleviate hepatic steatosis via supressing PPARγ transactivity and reducing the MRC contents in the liver of obese mouse." (PMID 26775807, 2016). "In addition, ASP markedly alleviated serum and liver lipid disorders and fatty liver via the upregulation of PPARγ expression and the activation of adiponectin-SIRT1-AMPK signaling." (PMID 27189109, 2016). "Several studies on mice with hepatic steatosis have shown that several transcription factors and components of the triacylglycerol metabolism such as PPARγ (Pparg), fatty acid synthetase (Fasn), SREBP-1c (Srebf1) and stearoyl-coenzyme A desaturase 1 (Scd1) are increasingly expressed in the liver." (PMID 28030540, 2016). "However, it is reported that treatment with PPARγ agonists, including pioglitazone, improved hepatic steatosis in patients with NAFLD, as well as in other animal models of NAFLD." (PMID 26035752, 2015). "PPARγ in hepatic tissue plays a key role in the development of hepatic steatosis." (PMID 26652604, 2015). "Furthermore, the deletion of PPARγ from hepatocytes protects mice against hepatic steatosis induced by a high-fat diet." (PMID 25875942, 2015). "This could be an early sign of developing hepatic steatosis in HFD-EPA/DHA mice since Pparγ activation triggers a signalling cascade contributing to the formation of lipid droplets in the cytoplasm." (PMID 26193881, 2015).
Hepatic steatosis (continued). "Studies have reported that PPARγ is expressed at elevated levels in the livers of obese animals, including KKAy mice, ob/ob mice, db/db mice, and 5HT-2cR mutant mice, as well as in lipoatrophic A-Zip/F1 mice, all of which develop severe hepatic steatosis." (PMID 24799887, 2014). "Hormonal regulation of PPARγ activity has been previously demonstrated in cases where PPARγ activity was stimulated by insulin treatment, and furthermore, its overexpression led to hepatic steatosis." (PMID 24789994, 2014). "However, hepatic PPARγ plays a critical role in hepatic steatosis and in whole-body lipid and glucose homeostasis." (PMID 24551137, 2014). "However, it has been reported that treatment with PPARγ agonists, including pioglitazone, improved hepatic steatosis in patients with NAFLD, as well as in other animal models of NAFLD." (PMID 24799887, 2014). "Moreover, administration of the PPARγ agonist, pioglitazone, for 30 days exacerbated the development of fatty liver and increased liver lesions." (PMID 24799887, 2014). "Additionally, the hepatic expression of FSP27, a recently identified direct mediator of PPARγ-dependent hepatic steatosis, was sharply increased by pioglitazone." (PMID 24799887, 2014). "In this study, we addressed the hypothesis that excess fat plays a central role in the pathogenesis of hepatic steatosis resulting from the overexpression of PPARα, PPARγ, and UCP2." (PMID 24086674, 2013). "Therefore, they propose that excess Pparγ activity can lead to the development of adipogenic hepatic steatosis." (PMID 22966224, 2012). "Taken together, these studies strongly implicate Pparγ in the development of hepatic steatosis." (PMID 22966224, 2012). "It is also likely that, in mice fed HFD, FGF21 could be exerting an important role in the liver where MR led to the transcriptional upregulation of Pparγ gene expression which correlated with improved glucose homeostasis and decreased hepatic steatosis." (PMID 23236485, 2012). "Given the antiobesity and anti-inflammatory properties of PPARα and PPARγ, pharmacological interventions targeting these transcription factors could be a promising strategy to treat hepatic steatosis in patients undergoing I/R." (PMID 22675337, 2012). "However, liver PPARγ regulates triglyceride homeostasis and contributes to hepatic steatosis, accumulating triglycerides in the liver." (PMID 22363472, 2012). "However, this is in contrast with studies showing hepatic overexpression of Pparγ in mouse models lead to adipogenic lipogenesis and that Pparγ and Cd36 are upregulated during hepatic steatosis." (PMID 23236485, 2012). "High-fat diet fed mice develop hepatic steatosis and have increased Pparγ expression." (PMID 22966224, 2012). "HNF4α may prevent hepatic stellate cell activation and thus ameliorate liver steatosis through transactivation of PPARγ." (PMID 22190905, 2011). "Therefore, ameliorating ERS to enhance PPARγ and promote lipolysis of LD mediated by Plin2 and Plin5 may be an effective way to prevent hepatic steatosis." (PMID 41373932, 2025). "Additionally, SCFAs reduce peroxisome proliferator-activated receptor gamma (PPAR-γ) expression, thereby enhancing oxidative metabolism in the liver and adipose tissue, which in turn decreases fat accumulation, mitigates hepatic steatosis, and improves insulin sensitivity." (PMID 40559421, 2025). "Furthermore, the upregulation of PPARγ induced by HFD has been described to lead to excessive hepatic lipid accumulation, and to be one of the underlying mechanisms of liver dysfunction, and progression to hepatic steatosis and T2D." (PMID 41614817, 2025). "However, whether celastrol can improve NAFLD in vitro and whether it can control fatty liver disease and overweight by modulating the PPARγ signaling pathway need to be clarified." (PMID 38276299, 2024).
Hepatic steatosis (continued). "Notably, considering the pivotal role of PPARγ in governing glucose and lipid metabolism, our finding that ufmylation on UFBP1 downregulated PPARγ expression may decipher the phenotypic alterations in hepatic steatosis, serum lipids and insulin sensitivity." (PMID 37660122, 2023). "It has been reported that ATF6 is important for attenuating hepatic steatosis under ER stress triggers, such as HFD, and that hepatic ATF6-conditional knockout causes lipid accumulation in the liver through the upregulation of the PPARγ pathway that facilitates lipogenesis." (PMID 37172729, 2023). "Moreover, inhibition of PPARγ reduced hepatic steatosis in mice fed with a high-fat diet." (PMID 38020065, 2023). "Naringenin inhibited HBx-induced hepatic steatosis by reducing the transcriptional activity of SREBP1c, LXRα, and PPARγ in HBx-transgenic mice and HepG2 cells, indicating that naringenin may be a potential therapeutic drug for inhibiting virus-induced metabolic disorders." (PMID 38130439, 2023). "It is less clear whether PPARγ is a significant trigger of liver steatosis in HMGB1ΔHep mice." (PMID 35333579, 2022). "However, PPARγ expression is markedly induced in the severe fatty liver." (PMID 35517790, 2022). "The hepatic PPARγ signal is highly expressed in the fatty livers, compared to normal mice, implicating the fact that, hepatic PPARγ may contribute more significantly to the development of fatty liver than LXRα, consistent with our findings." (PMID 31935815, 2020). "Studies have shown that PPARγ participates or regulates the fat deposition in liver by affecting the biological processes of hepatic lipid metabolism, insulin resistance, gluconeogenesis, oxidative stress, endoplasmic reticulum stress and inflammation, which all contribute to fatty liver." (PMID 32272794, 2020). "Therefore, modulating hepatic PPARγ as observed in this study might be responsible for the improved glucose metabolism whilst preventing excessive liver steatosis." (PMID 33076522, 2020). "Thus, it is difficult to elucidate whether PPARγ has a protective or detrimental role in liver steatosis." (PMID 31601915, 2019). "Moreover, immunohistochemical results showed that the expression of adipose differentiation-related protein, which is a target gene of PPARγ and localized on the surface of lipid droplets in hepatocytes, was increased in the hepatocytes in patients with a fatty liver compared with the normal liver." (PMID 30567368, 2018). "Thus, it is highly possible that hepatic steatosis phenotype in HFD-fed RORαLKO mice may be resulted from both upregulated PPARγ activation and suppressed PPARα transcriptional activity in the absence of RORα." (PMID 28757615, 2017). "Similarly, we also observed the attenuated hepatic steatosis and the decrease of SREBP1c, Pparγ, Scd1 and Cd36 involved in lipogenesis and lipid uptake, and increase of Cpt1, Acat and Echs1 involved in fatty acid oxidation in the liver of mice fed HFD and hemin." (PMID 28933767, 2017). "A very recent report suggests that rosiglitazone administration may exert opposite outcome on liver steatosis depending on liver PPARγ expression levels: RGZ worsen steatosis in PPARγ overexpressing mice fed a HFD and protected mice with low PPARγ expression level." (PMID 28115925, 2016). "Because the expression of CD36, DGAT2, and PLIN2 in liver is previously known to be regulated by PPARγ, a crucial nuclear transcription factor controlling cellular glucose and lipid metabolism, we also investigated whether PPARγ is involved in VPA-induced hepatic steatosis." (PMID 27034954, 2016). "Our data suggests that PPARγ may be an upstream regulator via which VPA induces hepatic steatosis." (PMID 27034954, 2016). "This PPARγ effect could be due to downregulation of proinflammatory cytokines and upregulation of antioxidant as well as redistribution of fatty acid from liver to adipose tissue resulting in the reduction of hepatic steatosis." (PMID 26246839, 2015).
Hepatic steatosis (continued). "Pparγ, and in particular Pparγ2, overexpression promotes hepatic fat accumulation (21, –, 24) in an Srebp-1c independent way, whereas a liver-specific deletion of Pparγ attenuates hepatic steatosis, highlighting the important role for Pparγ in fatty liver development (26, –, 28)." (PMID 26085100, 2015). "Expression of PPARγ in the liver of diabetic mice may enhance the development of hepatic steatosis." (PMID 26061387, 2015). "Thus, our results suggest that pioglitazone-mediated PPARγ hyperactivity may lead to adipogenic hepatic steatosis and hepatic adiposis in DIO mice." (PMID 26035752, 2015). "Given the inverse relationship between adipose eNOS expression and hepatic TG content, it is possible that restoration of adipose eNOS expression and the subsequent suppression of adipose tissue lipolysis might also contribute to how a PPARγ antagonist prevents HFD-induced fatty liver disease." (PMID 26317347, 2015). "However, HFD induces hepatic PPARγ expression accompanied by hepatic steatosis." (PMID 24398136, 2014). "Thus, PPARγ overexpression in KKAy mice and pioglitazone-mediated PPARγ hyperactivity may lead to adipogenic hepatic steatosis or hepatic adiposis." (PMID 24799887, 2014). "Similarly, mice with liver-specific PPARγ silencing are protected against hepatic steatosis." (PMID 22675337, 2012). "Thus, PPARγ induction appears to benecessary and sufficient for hepatic steatosis." (PMID 17389767, 2007). "Administration of Lactobacillus casei enhances hepatic PPARγ activity, which suppresses TLR4 signaling and reduces hepatic steatosis." (PMID 40564141, 2025). "(P)RR antagonists can inhibit the upregulation of hepatic PPARγ expression induced by a high-fat diet (HFD), improving hepatic steatosis and the progression of fibrosis." (PMID 40650317, 2025). "Our study further demonstrates that BBR activation of PPARγ leads to increased hepatic lipid accumulation and injury, along with a more pronounced reduction in CYP450 expression in hepatic steatosis." (PMID 39611414, 2025). "Paradoxically, pharmacological activation of PPARγ improves features of MASLD, including hepatic steatosis, ballooning, and inflammation, and also the stage of fibrosis in non-diabetic, prediabetic, and T2D patients with MASLD." (PMID 41438090, 2025). "Despite being a substrate of both PPARα and PPARγ, LDT409 was crucial for promoting hepatic fatty acid oxidation and reducing hepatic steatosis in HFD-fed mice." (PMID 38763495, 2024). "Hepatic steatosis is a key component of NAFLD pathophysiology, requiring the coordination between peroxisome proliferator-activated receptor alpha (PPARα) and PPARγ to balance fatty acid synthesis and oxidation." (PMID 39872862, 2024). "ACC, FASN, PPARG, CIDEC, and especially CIDEA are all involved in the onset of hepatic steatosis and lipid droplet fusion in MASLD." (PMID 39958875, 2024). "The administration of lycopene, another carotenoid, protected against hepatic steatosis and inflammation in BCO2-expressing mice through the activation of SIRT1 and PPARγ signals." (PMID 37018237, 2023). "CD36 is a target of PPARγ, and it is suggested that ERK signaling activates CD36 expression through PPARγ in hepatic steatosis." (PMID 36410795, 2023). "PPARγ induces hepatic steatosis through the expression of monoacylglycerol O-acyltransferase 1 gene (MGAT 1), a target gene of PPARγ for TG synthesis, and induces inflammation in CAC." (PMID 37569481, 2023). "To date, PPARγ and SREBP1 have been shown to be vital intermediary factors in mediating the Cu-induced liver steatosis, by orchestrating the transcriptional levels of the lipogenesis-related enzymes." (PMID 35966089, 2022). "On the other hand, studies have reported that PPARγ expression in the liver of patients with MAFLD increases and activates the expression of adipogenic genes and exacerbates hepatic steatosis." (PMID 36164476, 2022).
Hepatic steatosis (continued). "Hepatic knockdown of PPARγ in mice leads to resistance to high-fat-diet-induced hepatic steatosis and the decrease of genes involved in lipogenesis (SREBP1 and SCD1) and FA transporters regulated by PPARγ (CD36)." (PMID 35276938, 2022). "The expression of PPARγ and lipogenesis-related genes, such as the fatty acid transporter CD36, are significantly elevated in the liver during hepatic steatosis, along with increased TAG level in the liver." (PMID 32272794, 2020). "We also examined GDS in terms of the regulation of hepatic steatosis and inflammation through the HTR2A/PPARγ pathway." (PMID 32477107, 2020). "Other studies have also shown that extrahepatic tissue-specific (i.e. muscle- or adipocyte-) PPARγ deletion promotes NAFLD and that TZD-treatment exacerbates fatty liver disease in muscle-specific PPARγ KO mice." (PMID 32963510, 2020). "The expressions of PPARγ, FSP27 and CD36 decreased with the suppression of hepatic steatosis in the LIrs1KO mice, whereas they were maintained in the LIrs2KO mice." (PMID 27708333, 2016). "Thus, we hypothesize that binge drinking initially affects SREBP1c or ChREBP to develop a mild steatosis primarily by fatty acid de novo synthesis, which later induces a sufficient level of acetylated PPARγ and its target genes, and ultimately aggravating hepatic steatosis." (PMID 27404390, 2016). "PPARγ and DGAT are significantly up-regulated after acute EtOH administration and are involved in EtOH-induced fatty liver in mouse." (PMID 27298813, 2016). "KBH-1 exhibits alleviating effects by improving hepatic steatosis and leptin resistance by up-regulating the activation of AMPK and suppressing the expression of PPARγ." (PMID 27618865, 2016). "Based on these studies, we investigated the involvement of PPARγ- and CD36-regulated lipid metabolism in VPA-induced hepatic steatosis." (PMID 27034954, 2016). "In a study conducted with mice PPARγ was shown to regulate TAG homeostasis and to contribute to hepatic steatosis." (PMID 26034989, 2015). "Phosphorylation of eIF2α downstream of PERK affects the transcriptional activity of C/EBPs, PPARγ, and SREBP-1c thereby leading to lipid accumulation and hepatic steatosis under high-fat-diet conditions." (PMID 22195283, 2012). "However, expression of PPARγ does not appear to be linked to hepatic steatosis in humans." (PMID 20182551, 2009). "Our results indicated that GA downregulated the PPARγ signaling by increasing hepatic IRF6 levels, which then weakened lipid synthesis and accumulation by downregulating lipogenesis-related factors, ultimately relieving hepatic steatosis and liver damage." (PMID 40235530, 2025). "Furthermore, inhibition of PPARγ with T0070907 alleviated Snhg3- and SND1-induced Cd36 and Cidea/c increase and improved Snhg3-aggravated hepatic steatosis." (PMID 39436790, 2024). "Also, we demonstrated that celastrol inhibited the transcriptional activity of PPARγ, thereby decreasing the Fabp3, Fatp1, MCAD, Fads2, and ACC1 mRNA expression in OA-induced hepatic steatosis cells." (PMID 38276299, 2024). "Based on the current understanding, it is believed that hepatic steatosis is primarily driven by the activity of hepatocyte PPARγ, as opposed to PPARα." (PMID 39200340, 2024). "Selective PPARγ modulators (amorfrutins) have been shown to improve insulin sensitivity, dyslipidemia, liver steatosis, and atherosclerosis, without increasing body weight." (PMID 37096195, 2023). "More importantly, we revealed a mechanism that ICAE may alleviate liver steatosis by reducing the protein expression of ADRP and PPARγ." (PMID 35432557, 2022). "The decrease in PPARγ and CD36 levels suggests a protective response against hepatic steatosis." (PMID 35276938, 2022). "PXR promoted liver steatosis through regulations on lipogenesis and lipid catabolism in largemouth bass, but the lipogenesis enhancement was achieved majorly in a PPARγ-dependent manner rather than a SREBP1-dependent manner." (PMID 35966089, 2022).